LOXL1 (lysyl oxidase like 1)
Diseases named in the same sentence as LOXL1 in open-access papers (continued):
Sharing a sentence is not in itself a finding about the gene and the disease.
tumor (continued). "Previous study revealed that LOXL1 could be upregulated by TGF-β secreted by tumor cells." (PMID 38267662, 2024). "Increased mutation rates and genomic instability are inherent characteristics of tumour progression, and an increase in LOXL1 mutations may simply be a red herring rather than a cause of cancer progression." (PMID 34105806, 2021). "Thus, in MM134 cells, LOXL1 is required for tumor growth and invasion." (PMID 33616307, 2021). "We wondered whether increased LOXL1 expression was involved in the resistance of tumor cells to IR." (PMID 32424143, 2020). "To investigate whether LOXL1-mediated collagen matrix alignment may have a role in tumor growth, we collected xenograft tumors formed by subcutaneous co-implantation into SCID mice of the A549 NSCLC cell line with the different CAFs with varying expression of LOXL1." (PMID 31121900, 2019). "The results revealed a predominantly positive correlation between CNA and LOX family members in most tumours, with only a few exceptions noted, such as LOX in LIHC, LOXL1 in TGCT and LOXL4 in HNSC and LGG." (PMID 40179101, 2025). "The results indicated a significant increase in the expression of INF-γ and TNF-α in the tumor tissues of mice from the sh-LOX, sh-LOXL1, sh-LOXL2, sh-LOXL3, and sh-LOXL4 groups compared to the sh-NC group." (PMID 40270974, 2025). "Similar to the in vivo tumourigenesis results, tumour proliferation was inhibited despite the increase in ECM collagen and myofibroblast content induced by LOXL1." (PMID 39881364, 2025). "The results demonstrated a significant decrease in the expression of Ki67 protein in tumor tissues from sh-LOX, sh-LOXL1, sh-LOXL2, sh-LOXL3, and sh-LOXL4 mice, compared to the sh-NC group." (PMID 40270974, 2025). "However, some studies have also suggested that LOXL1 may have a tumor-suppressive function." (PMID 40786111, 2025). "Flow cytometry analysis revealed a significant reduction in the proportion of M2 macrophages in the tumor tissues of sh-LOX, sh-LOXL1, sh-LOXL2, sh-LOXL3, and sh-LOXL4 groups of mice compared to the sh-NC group." (PMID 40270974, 2025). "Although LOXL1-induced ECM collagen and myofibroblast content increased, tumour proliferation was inhibited." (PMID 39881364, 2025). "RT-qPCR and WB techniques were used to detect the expression of LOX, LOXL1, LOXL2, LOXL3, and LOXL4 in tumor tissues." (PMID 40270974, 2025). "To further assess the ECM environment of the tumours, we performed immunohistochemical staining to evaluate the expression of HSF4, LOXL1, MASSON, and α-SMA." (PMID 39881364, 2025). "For example, α11β1 in NSCLC-derived CAFs induced the lysyl oxidase-like 1 (LOXL1) secretion, an ECM cross-linking enzyme, to initiate collagen deposition, matrix stiffness, and tumor invasion." (PMID 40352270, 2025). "Preliminary observations indicate a decrease in the tumor volume and weight of mice in the sh-LOX, sh-LOXL1, sh-LOXL2, sh-LOXL3, and sh-LOXL4 groups compared to the sh-NC group." (PMID 40270974, 2025). "LOXL1 stabilizes BAG family molecular chaperone regulator 2 (BAG2) by preventing K186 ubiquitination, thereby inhibiting tumor apoptosis." (PMID 40786111, 2025). "Immunofluorescent staining revealed increased infiltration and exhaustion of CD8+ T cells in the tumor tissues of mice in the sh-LOX, sh-LOXL1, sh-LOXL2, sh-LOXL3, and sh-LOXL4 groups, compared to the sh-NC group." (PMID 40270974, 2025). "Integrin α11β1 influences lysyl oxidase-like 1 (LOXL1), an ECM cross-linking enzyme critical for tumor growth and invasion." (PMID 38539448, 2024). "Larger tumor size (T3-4), regional lymph nodes metastasis (N2-3) and advanced tumor stage (stage III-IV) were more commonly detected in patients with high LOXL1 expression." (PMID 38267662, 2024). "Given the importance of the interaction between tumor and TME in tumor progression and response to immunotherapy, the role of LOXL1 in anti-tumor immunity was also systematically evaluated." (PMID 38267662, 2024).
tumor (continued). "Initially, LOXL1 and LOXL4 silencing by methylation were shown to have tumor-suppressive effects in human bladder cancer, while compensation experiments inhibited RAS-mediated ERK activation and reduced tumor-cell colony formation." (PMID 36293126, 2022). "LOXL1 can stabilize BAG family molecular chaperone regulator 2(BAG2) by blocking K186 ubiquitination and inhibit tumor apoptosis." (PMID 36293126, 2022). "Later studies on NSCLC demonstrated that α11β1 signaling leads to the upregulation of lysyl oxidase like-1 (LOXL1) and, subsequently, increased collagen crosslinking, stromal stiffness, and tumor growth and progression." (PMID 36003785, 2022). "COL5A1, LOXL1, and TMEM63C expression levels were significantly higher and LYSMD3 expression levels were significantly lower in tumor tissues than in the paired normal tissues." (PMID 35152572, 2022). "Though there were no existing evidence proved that Loxl1 can direct regulate the inflammatory cytokines secretion, according to the association analysis, Loxl1 was significantly associated with intratumoral inflammation and interleukin-4 expression level in frozen tumor tissues." (PMID 34923484, 2021). "LOXL1, like other Lysyl oxidase (LOX) family members, has an established role in modifying the tumor microenvironment by crosslinking collagens and elastin in the extracellular matrix." (PMID 33790946, 2021). "The results of the in vivo experiments demonstrated that the overexpression of LOXL1 in CRC cell lines drastically inhibited metastatic progression and tumour growth." (PMID 32912229, 2020). "Moreover, LOXL1 overexpression may induce EMT that is well known to promote tumor cell migration." (PMID 33095806, 2020). "We analyzed clinical samples to detect the expression levels of LOXL1 and LOXL4 in both tumor and matched adjacent tissues." (PMID 32424143, 2020). "Overexpression of LOXL1 in this model (CAF094-LOXL1) significantly enhanced the number and depth of tumor cell invasion compared to the invasion in CAF094-Mock-populated matrices (p < 0.001)." (PMID 31121900, 2019). "Our results show that LOXL1, through regulation of integrin α11 in CAFs, mediates collagen fiber alignment in NSCLC stroma to support tumor progression." (PMID 31121900, 2019). "In these groups several noteworthy changes include the ECM cross-linking proteins, lysyl oxidase, lysyl oxidase-like 1, and tissue transglutaminase II (TGM2), which have been previously shown to play a role in tumor stiffness and progression." (PMID 30154546, 2018). "Negative correlation was found between LOXL1 expression and the infiltration abundance of anti-tumor immune cells such as CD8 + T cell, CD4 + T cell, B cell, and dendritic cell in COAD, BRCA, and HNSC." (PMID 38267662, 2024). "Furthermore, quantitative RT-PCR analysis of 38 clinical sample pairs revealed a pronounced upregulation of LOXL1 mRNA in CRC tissues, compared with non-tumor tissues." (PMID 38267662, 2024). "Elevated expression of LOXL1, LOXL4 and GUCA1A was detected in tumour cells." (PMID 39286023, 2024). "The result revealed a negative correlation between LOXL1 expression and favorable gene signatures associated with ICB response, such as tumor-infiltrating lymphocytes (TILs)." (PMID 38267662, 2024). "LOXL1 prevented BAG2-K186 ubiquitylation and promoted tumor cell survival." (PMID 39286023, 2024). "Stiffness of the tumor micro-environment can be controlled by collagen crosslinkers such as the Lysyl oxidases, which consist of Lysyl oxidase (LOX) and the Lox-like 1–4 (LOXL1–4) proteins; amine oxidases that share high similarity in their copper-dependent catalytic domain." (PMID 35292774, 2022). "Furthermore, LOXL1 secreted by tumor cells can interact with other types of cells in TME and accelerate tumor progression." (PMID 36293126, 2022).
tumor (continued). "Specifically, the increased expression of LOX, LOXL1 and LOXL2 appears to be correlated with similar trends in terms of patient survival, tumour infiltrates and correlation with expression of genes involved in tumour-related processes." (PMID 35800439, 2022). "This family comprises five cooper-dependent amine oxidases (LOX, LOXL1, LOXL2, LOXL3, and LOXL4), which are involved in several hallmarks of cancers, such as tumor microenvironment remodeling, invasion/migration, growth, inflammatory response, genomic stability, and resistance to chemotherapy." (PMID 36076905, 2022). "Alternatively, increases in BMP1 may have tumour suppressive effects in Ras transformed cancers, where post-translational processing in cells highly expressing LOX and LOXL1 would increase levels of the tumour suppressive LOX pro-peptide." (PMID 33513979, 2021). "Along with that, the expression level of LOXL1 was higher in the tumor tissues of GC patients with PD than in GC patients without PD in the GSE15459 dataset." (PMID 33095806, 2020). "Since LOXL1 is highly homologous to LOX, we hypothesized that its tumour suppressor activity is also dependent on its intracellular function." (PMID 32912229, 2020). "Furthermore, secretion of LOXL1 by CAF in the TME mediated collagen fiber alignment to support NSCLC tumor growth and tumor cell invasion." (PMID 31121900, 2019). "It has also been suggested that LOXL1 and LOXL4 may have tumour-suppressing roles in bladder cancer." (PMID 26804196, 2016). "The mRNA expression level of six soluble factors already recognized in cancer biology (POSTN, TNC, CSPG2, LOXL1, ATRN, FBS1) increases in response to IGF-I stimulation, suggesting that these factors play some role in stimulating tumour cell proliferation and metastasis." (PMID 20051100, 2010). "LOXL1, FBLN5, and ITG-αvβ3 on the surface of vascular endothelial cells (VECs) may form a complex that regulates the FAK and MAPK pathways in VECs, promoting tumor angiogenesis." (PMID 40786111, 2025). "The mCAF subset of the tumor stroma specifically expressed transcripts of a large variety of ECM-related genes, such as glycoproteins (Dcn, Lum, and Vcan), structural proteins (Col14a1), matricellular proteins (Fbln1, Fbln2, and Smoc), and matrix-modifying enzymes (Lox and Loxl1)." (PMID 30514914, 2018). "qPCR quantification of the relative expression of the five candidate genes LOXL1, SCRN1, VAMP5, SERPINB1, and TMSB4X in cryopreserved tumor tissues from validation set 1 was correlated to the CSIs measured in the corresponding fresh tissue samples of the same tumor lesions." (PMID 26799424, 2016). "Therefore, compared to patients with LOXL1‐non‐mutant tumours, patients with LOXL1‐mutant tumours not only had a lower survival rate but also higher levels of transcripts of genes associated with biological processes, such as cell proliferation and immune activation." (PMID 34105806, 2021).
cancer (44 papers, 2010 to 2025). A tumor composed of atypical neoplastic, often pleomorphic cells that invade other tissues. "This article provides a comprehensive review of the structure and function of LOXL1, along with its associations with cancer." (PMID 40786111, 2025). "MCT1/2 reduces the pH of the acidic extracellular environment by inducing lactate accumulation and substantially increases MMP2/9 protein expression, thus participating in LOXL1-associated cancer metastasis." (PMID 40786111, 2025). "High expression of LOXL1 in cancer-associated fibroblasts (CAFs) has been shown to enhance NSCLC tumorigenicity, while increased LOX activity also helps promote increased invasion and migration of NSCLC." (PMID 35205728, 2022). "Several genes involved in the GESGC have been reported to be associated with human cancer, including LOXL1, RAB31 and CBR1." (PMID 29957874, 2018). "This study suggests that the LOXL1 protein can serve as a potential drug target for inhibiting malignant tumour metastasis." (PMID 40786111, 2025). "Other functions of the LOXL1 protein, such as the inhibition or promotion of cancer occurrence, have also been proposed." (PMID 40786111, 2025). "Studies have shown that LOXL1 protein expression varies across different cancer tissues and cell lines." (PMID 40786111, 2025). "This article primarily examines the structure, function, and role of LOXL1 in cancer initiation and progression." (PMID 40786111, 2025). "We conducted a comprehensive literature search on PubMed and Web of Science using the keywords “LOXL1” and “Cancer”." (PMID 40786111, 2025). "Our study unveiled an increased expression of LOX and LOXL1‐3 across various cancer types, whereas LOXL4 expression demonstrated an inverse trend." (PMID 40179101, 2025). "Due to differences in emphasis and the complex nature of cancer development, which is influenced and regulated by multiple factors, understanding the impact of LOXL1 on CRC is very important for the subsequent diagnosis and treatment." (PMID 40786111, 2025). "Lysyl oxidase like 1 (LOXL1), a copper-dependent amine oxidase, is implicated in various cancers, influencing cell proliferation and metastasis through extracellular matrix (ECM) remodeling." (PMID 38267662, 2024). "To examine the prognostic value and immune regulatory influence of LOXL1 across pan-cancer, we analyzed its expression in 24 solid tumor types from TCGA database." (PMID 38267662, 2024). "LOXL1 has been found to promote extracellular lactate accumulation under low pH conditions, upregulating MCT1/2 expression, which suggests that LOXL1 plays a role in cancer metastasis under hypoxic conditions." (PMID 39247609, 2024). "Metastatic tumors displayed elevated expression of LOXL1 compared with primary tumors and normal tissues across several cancers from TNM plotter database." (PMID 38267662, 2024). "The results, which is sourced from UALCAN, revealed that LOXL1 was dysregulated in 13 types of cancers, with 12 of them showing significant upregulation." (PMID 38267662, 2024). "It was observed that adaptive immune cell, notably CD8 + T cells known for their positive impact on survival and immunotherapy response in various cancers, was markedly lower in cases with heightened LOXL1 expression." (PMID 38267662, 2024). "Specifically, we detected elevated expression levels of Lox, Loxl1, and Loxl3 in mesenchymal cancer cells." (PMID 37156840, 2023). "In the present study, PTC cells with high LOXL1 expression showed more aggressive behavior, consistent with the results obtained for other cancers." (PMID 35152572, 2022). "As expected, these CNVs caused differential gene expression at these loci, such as LOXL1 and FAM81A implicated in cancer progression." (PMID 35986270, 2022). "Increasing evidence suggests that Loxl1 deficiency contributes to the pathogenesis of several other diseases, such as cancer, which indicates the importance of LOXL1 and elastin in organ morphology maintenance." (PMID 34105806, 2021).
cancer (continued). "The main roles of LOXL1 include elastin homeostasis and matrix remodelling during injury and the development of fibrosis and cancer." (PMID 34440405, 2021). "There has been little research thus far examining the use of BMP1 inhibitors in combination with chemotherapeutics to specifically treat LOX/LOXL1 overexpressing cancers." (PMID 33513979, 2021). "Different protein isoforms, their intra and extracellular locations, the proteolytic cleavage status in the case of LOX and LOXL1, and other cellular events contribute to these different outcomes in cancer." (PMID 33669630, 2021). "We used GSC11, a cancer stem cell line, to perform colony formation and apoptotic assays after depletion of LOXL1 with two distinct shRNAs and observed the consistent results with LN18." (PMID 32424143, 2020). "In the present study, we described the cancer-promoting effect of LOXL1, which directly originated from its intracellular partners." (PMID 32424143, 2020). "Increasing evidence has revealed that the lysyl oxidase, LOXL1 is involved in the malignant progression of cancer." (PMID 32912229, 2020). "Using cancer-associated fibroblast (CAF) with either a knockdown or overexpression of LOXL1, we demonstrated a role for LOXL1 in collagen matrix remodeling and collagen fiber alignment in vitro and in vivo in a NSCLC xenograft model." (PMID 31121900, 2019). "Further elucidation of the functions and mechanisms of LOXL1 could provide new insights into cancer treatment." (PMID 40786111, 2025). "The genetic alterations of LOXL1 in pan-cancer were also assessed using cBioPortal database." (PMID 38267662, 2024). "Additionally, using the TISIDB database, we explored LOXL1 expression across different immune subtypes in various cancers." (PMID 38267662, 2024). "Additionally, LOXL1's potential as an immunotherapy response indicator was assessed, along with its role in pan-cancer." (PMID 38267662, 2024). "In addition, Lysyl oxidase (LOX) and its family members LOXL1-4, the copper-dependent amine oxidases playing critical roles in ECM crosslinking and remodeling, are implicated in cancer progression and metastasis." (PMID 36003792, 2022). "LOXL1 was highly expressed in normal colon tissues compared with cancer tissues." (PMID 32912229, 2020). "To date, only a few studies have clarified the correlation between LOXL1 and cancer development." (PMID 33058284, 2020). "In contrast, relatively little is known about the role of LOXL1 in cancers." (PMID 31121900, 2019). "Additionally, it explores the potential applications of LOXL1 in cancer research, offering theoretical insights and references that may support clinical diagnosis and treatment strategies for cancer." (PMID 40786111, 2025). "Although these studies did not directly examine changes to the LOX family, it is possible that dysregulation of ADAMTS2 and14 could be altering the regulation of LOX and LOXL1 and contributing to cancer progression reported and is an interesting area for further investigation." (PMID 33513979, 2021). "In addition, WTAP also regulates the expression of certain genes associated with cancer cell movement, such as chemokine ligand 2 (CCL2), CCL3, matrix metalloproteinase 3 (MMP3), lysyl oxidase like 1 (LOXL1), hyaluronic acid synthase 1 (HAS1) and thrombospondin 1 (THBS1)." (PMID 32943100, 2020). "LOXL1/4 might suppress cancer cell growth by blocking Ras/ERK signaling." (PMID 29732010, 2018). "Concerning cancer cell lines, the expression of LOX, LOXL1, LOXL2, LOXL3 and LOXL4 was highest in GBM, GBM, GBM, SKCM and PAAD, while lowest in CLL, CLL, LCML, DLBC and CLL, respectively." (PMID 40179101, 2025). "Our findings revealed a marked enrichment of LOXL1 in wound healing and TGF-β dominant subtypes and a downregulated in IFN-γ dominant subtypes in cancers including colorectal, suggesting LOXL1’s immunosuppressive role in pan-cancer." (PMID 38267662, 2024).